MRE11 (MRE11 double strand break repair nuclease)
Diseases named in the same sentence as MRE11 in open-access papers (continued):
Sharing a sentence is not in itself a finding about the gene and the disease.
bladder cancer (25 papers, 2008 to 2025). "MRE11 expression and association with disease-specific (bladder cancer) mortality (DSM), defined as death from bladder cancer." (PMID 36383379, 2022). "Previously, we found that bladder cancer patients with high MRE11 expression paradoxically have shown higher survival rates after radiation therapy, despite MRE11 being involved in repair of DNA DSB caused by ionising radiation." (PMID 33558481, 2021). "In two different studies of bladder cancer patients, high MRE11 expression was associated with better cancer-specific survival in patients who underwent radiotherapy rather than a cystectomy." (PMID 30176843, 2018). "In addition, MRE11 protein expression was proved to be a predictive factor associated with survival following bladder cancer radiotherapy." (PMID 31221177, 2019). "In the combined radiotherapy cohort, in the group with low CK5 expression (less than its median) CK20 and MRE11 were associated with a lower risk of bladder cancer death (HR per unit increase 0.994, 95% CI: 0.990–0.998, p = 0.003, and 0.991 95% CI: 0.985–0.996, p = 0.0007, respectively)." (PMID 29991697, 2018). "In addition to ATM, germline mutations in MRE11 has been shown to be predictive of radiotherapy response in bladder cancer, while inherited defects in DSB repair genes NBS1 and Lig4 have been linked to fatal complications from low doses of radiotherapy." (PMID 28055970, 2017). "The aims of the present study were to further our understanding of the mechanisms underlying the low tumour MRE11 protein expression seen in poorly responding bladder cancer patients, as potentially this could be exploited clinically, and to determine the level of control, relative to transcription." (PMID 24625413, 2014). "More specific to our research, a report has shown that mocetinostat can enhance the radiosensitivity of bladder cancer cells, which appeared to be mediated through reducing the protein levels of MRE11, RAD51, and NBS1 involved in DSB repair." (PMID 39682293, 2024). "HDACi panobinostat promotes MRE11 degradation, which in turn promotes radiosensitivity of bladder cancer cells by enhancing DNA damage." (PMID 38287022, 2024). "Accumulation of the truncated Mre11 form found in NaBut-treated transformed cells correlates with the results obtained in bladder cancer cells." (PMID 35408878, 2022). "This demonstrates that the cleavage product generated by SPRTN is missing the C-terminal of MRE11, similar to the TR-MRE11 form in some bladder cancer cells." (PMID 33558481, 2021). "An E3 ligase, cIAP2, is upregulated by HDAC inhibition in bladder cancer cells; elevated cIAP2 increases MRE11 turnover by potentiating its ubiquitination, resulting in the decreased ability of MRE11 to repair DSBs in DDR." (PMID 34440334, 2021). "Panobinostat-induced downregulation of meiotic recombination 11 homolog (MRE11) enhances radio-sensitization of bladder cancer cells by promoting MRE11 ubiquitination that relies on the upregulated E3 inhibitor of apoptosis protein 2 (cIAP2)." (PMID 33117804, 2020). "At least two markers (MRE11 and CK20) were significantly associated with survival in patients with bladder cancer, and a further three markers showed results warranting expert follow-up." (PMID 29991697, 2018). "In conclusion, we have found that, in muscle-invasive bladder tumour samples and a panel of bladder cancer cell lines, MRE11 expression is regulated at the post-transcriptional level, while RAD50 and NBS1 undergo transcriptional control." (PMID 24625413, 2014). "The same Taqman assay was used to detect MRE11 RNA expression in a panel of bladder cancer cell lines and a similar discordance was seen between RNA expression and protein expression, by western blotting (p=0.42)." (PMID 24625413, 2014). "In bladder cancer, MRE11 has been shown to exhibit predictive properties for radiotherapy treatment." (PMID 24927325, 2014).
bladder cancer (continued). "The only current predictive DDR biomarker for radiotherapy response is MRE11 protein expression in bladder cancer, which has been independently validated." (PMID 25415046, 2014). "MRE11 RNA and protein levels were measured in 88 bladder tumour patient samples, by real-time PCR and immunohistochemistry respectively, and a panel of eight bladder cancer cell lines was screened for MRE11, RAD50 and NBS1 mRNA and protein expression." (PMID 24625413, 2014). "Furthermore, we performed a reciprocal mass spectrometry screen of the MRE11 interactome in T24 urinary bladder cancer cells, which identified p97 as one of the top interaction partners of MRE11, supporting our SILAC mass spectrometry findings." (PMID 34038735, 2021). "The presence of this DNA repair-defective TR-MRE11 could explain our previous finding that the high MRE11 protein expression by immunohistochemistry correlates with improved survival following radical radiotherapy in bladder cancer patients." (PMID 33558481, 2021). "In addition, we mined variation and expression data from the TCGA bladder cancer cohort for the relationship of MRE11 isoform usage and rs1805363." (PMID 31942442, 2019). "Similarly, MRE11 ubiquitination is also involved in bladder cancer." (PMID 34440334, 2021). "However, we recently observed a truncated version of MRE11 in a bladder cancer cell line, which is still detected by the antibody used in this study, and we hypothesize that this might act in a dominant-negative fashion." (PMID 30885775, 2019). "However, the reason why high MRE11 protein expression, by immunohistochemistry using an antibody with an epitope spanning amino acids 182–582, is associated with better survival rate in bladder cancer patients after radiotherapy has not yet been explained." (PMID 33558481, 2021). "Monoclonal cell lines expressing FL or TR-MRE11 were established in both MRE11 KD RT112 and MRE11 KD VM-CUB1 bladder cancer cells using lentivirus." (PMID 33558481, 2021). "Choudhry and colleagues examined protein expression of MRE11, RAD50, NBS1, ATM, and H2AX by immunohistochemistry in pretreatment tumor specimens from 179 bladder cancer patients receiving radical radiotherapy." (PMID 26198537, 2015). "In contrast, our findings suggest that in bladder cancer transcriptional control dominates for RAD50 and NBS1, but MRE11 expression is regulated at the post-transcriptional level." (PMID 24625413, 2014). "As MRE11, NBS1, RAD50, ATM, and H2AX interact with each other to facilitate DSB damage signalling, we hypothesized that there may be a gene dosage effect in our study, with subjects with increasing numbers of high risk alleles having an increased risk of bladder cancer." (PMID 18638378, 2008). "Low MRE11 expression was predictive of poor response to radiotherapy, rather than being a prognostic marker in bladder cancer, as expression was not correlated with outcome in our surgical cohort." (PMID 24625413, 2014). "We used an RT112 bladder cancer cell line knocked down for endogenous MRE11 and re-expressing an MRE11 construct containing either the full length MRE11 coding sequence (MRE11 isoform 1) or the MRE11 coding sequence lacking MRE11 exon 16 (MRE11 isoform 2)." (PMID 31942442, 2019). "Our polysome assay results suggest that the rate of translation of MRE11 may not be an important determinant of MRE11 protein expression in bladder cancer, although we only studied two cell lines." (PMID 24625413, 2014). "Lack of the Mre11 C-terminal decreased DNA repair efficiency, due to abolished recruitment of Mre11 to DSB, which consequently led to the radiosensitization of bladder cancer cells." (PMID 35408878, 2022).
colorectal cancer (19 papers, 2010 to 2023). A primary or metastatic malignant neoplasm that affects the colon or rectum. "Here, we explored the clinicopathological significance and prognostic value of MRE11 expression in colorectal cancer (CRC), a leading cause of cancer-related deaths worldwide." (PMID 37173905, 2023). "Mutations in MRE11 are associated with increased susceptibility to colorectal cancer, especially in relation to increased microsatellite instability." (PMID 30769804, 2019). "Colorectal cancer cells harboring biallelic Mre11 mutations were more sensitive to the PARP inhibitor, LT-626 and stable overexpression or knock-down of Mre11 in cell lines correlated with sensitivity." (PMID 28314386, 2017). "Mutations in MRE11 are common in microsatellite-unstable colorectal cancer and cause a higher sensitivity to radiation." (PMID 24338765, 2014). "Somatic mutations in MRE11, however, are frequently detected in colorectal cancers with MSI and have also been suggested for MSI-positive ECs." (PMID 24927325, 2014). "Furthermore, complete loss of MRN-complex in MSI positive colorectal cancers is a frequent event, whereas loss of MRE11 in breast tumours is found only in 9% of cases." (PMID 24927325, 2014). "MRE11 mutations occur in the majority of mismatch repair (MMR)-defective primary colorectal cancers, and approximately 15% of colorectal cancers display microsatellite instability (MSI)." (PMID 30769804, 2019). "Several studies have confirmed defective MRE11 expression in MSI colorectal cancers, and interestingly, a mild defect in either MRE11 or RAD50 is adequate to downregulate RAD50 and overall MRN expression in MSI tumours." (PMID 30769804, 2019). "Reduced Mre11 expression has been implicated in mediating sensitivity to PARP inhibition in endometrial and colorectal cancers." (PMID 28314386, 2017). "Furthermore, advanced colorectal cancers with MSI are more sensitive to irinotecan, and low MRE11 or RAD50 expression in these tumours is associated with increased chemosensitivity, and predicts better outcomes." (PMID 30769804, 2019). "Furthermore, elevated PALB2 expression was associated with poorer overall survival, suggesting that PALB2 expression levels may also serve as a novel prognostic factor for colorectal cancer patients, similar to MRE11." (PMID 37372450, 2023). "MRE11, a part of the MRN complex involved in double-strand break (DSB) repair, is connected to colorectal cancer (CRC) patients’ prognosis." (PMID 36324569, 2022). "Here, we show that the RSR is efficient in primary CSCs from colorectal cancer (CRC-SCs), and describe unique roles for PARP1 and MRE11/RAD51." (PMID 33531658, 2021). "Recently MRE11, the nuclease component of the RAD50/MRE11/NBS1 (MRN) nuclease complex, has attracted attention as a potential key factor in the growth, invasion, and metastasis of a number of solid tumors including breast, lung, ovarian, and colorectal cancer." (PMID 33927349, 2021). "Microsatellite instability (MSI) accounts for 10-15% of colorectal cancer (CRC) and is hypothesized to lead to HR defects due to altered expression of Mre11, a protein required for double strand break (DSB) repair." (PMID 25685067, 2015). "Two colorectal cancer cell lines, DLD-1 and HCT116, and their corresponding isogenic AKT isoforms knockout cell lines were used to show whether AKT1 or AKT2 were activated after exposure to ionizing radiation and their effect on the expression of MRE11 and DNA-PKcs." (PMID 24338765, 2014).
colon cancer (18 papers, 2012 to 2025). "Pathogenic variants within MRN complex genes have been implicated in breast, ovarian, prostate, colon cancers and gliomas; however, the hundreds of VUSs within MRE11, RAD50, and NBS1 precludes the application of these data in genetic guidance of carriers." (PMID 36358700, 2022). "For example, the telomerase-positive HCT116 colon cancer cell line used here harbors a mutation in MRE11, which impairs binding to NBS1 and Rad50 and suppresses ATM activation in response to replication stress." (PMID 27602331, 2016). "Deficiency in MRE11 occurs not only in colon cancer but also other solid tumors with deficient mismatch repair." (PMID 25310185, 2014). "Notably, MRE11 protein deficiency has been recently observed to be associated with improved survival of stage III colon cancer patients, independently of treatment." (PMID 26735576, 2016). "In addition to the fact that MSI is associated with downregulation of MRE11 in colon cancer cells, which is essential for optimal signaling of ATM in response to DSBs, HCT116 cells also carry a mutation (c3380C > T) in one ATM allele, affecting ATM expression to half of normal." (PMID 33888065, 2021). "Here, S6K1 overactivation by genetic deletion of PTEN can suppress DNA repair after irradiation by downregulating the MRN complex member MRE11 in colon cancer cells." (PMID 39408794, 2024). "In colon cancer, the mutant R248W binds to Mre11, while R273H binds to NF-Y, Mre11, or YAP1 in cell lines HT29, SW620, SW480, respectively." (PMID 31795192, 2019). "This study investigated MRE11 status and its association with prognosis, survival and drug response in patients with stage III colon cancer." (PMID 25310185, 2014). "Taken together, our results present strong support for the role of both AKT1 and AKT2 isoforms in the response to ionizing radiation and their interaction with DNA-PKcs and MRE11 in colon cancer cells." (PMID 24338765, 2014). "The role of AKT isoforms has been investigated in relation to radiation response and their effects on DNA repair proteins (DNA-PKcs and MRE11) in colon cancer cell lines." (PMID 24338765, 2014). "Colon cancers deficient in mismatch repair (MMR) may exhibit diminished expression of the DNA repair gene, MRE11, as a consequence of contraction of a T11 mononucleotide tract." (PMID 25310185, 2014). "Furthermore, AKT may inhibit DSB repair in colon cancer cells via inhibition of MRE11 by p70S6 kinase, suggesting the presence of a feedback loop between MRE11 and AKT." (PMID 33927349, 2021). "Glycolytic reprogramming facilitated lactate accumulation and meiotic recombination 11 homolog 1 (MRE11) lactylation, thereby provoking resistance to olaparib and cisplatin in colon cancer." (PMID 40740652, 2025). "A previous study showed that this AKT activation has a suppressor role for DNA repair via S6K1, effects accompanied by a reduced expression of MRE11, RAD50, and NBS1 in colon cancer." (PMID 39408794, 2024). "In colon cancer cohort (TCGA-COAD) data analysis, the Kaplan–Meier curves revealed that high MRE11 tends to correlate with worse survival probability (n = 438, p = 0.290)." (PMID 37173905, 2023). "Pavelitz and colleagues found that loss of MRE11 is associated with improved overall survival (OS) and long-term disease-free survival (DFS) in a small cohort of patients with stage III colon cancer, independent of treatment." (PMID 37173905, 2023). "Specifically, MRE11 deficiency is associated with improved overall survival (OS) and long-term disease-free survival (DFS) in patients with stage III colon cancer independent of treatment, suggesting that MRE11 status has value as a prognostic marker in CRC." (PMID 27930716, 2016).
ataxia telangiectasia (12 papers, 2011 to 2025). Ataxia-telangiectasia is the association of severe combined immunodeficiency (affecting mainly the humoral immune response) with progressive cerebellar ataxia. "ATM (mutated in ataxia-telangiectasia (A-T) and members of the Mre11/Rad50/Nbs1 (MRN complex) play key roles in this process." (PMID 26512707, 2015). "The type 2-shape of MRE11 kinetics generally reflects impaired or absent MRE11 foci as observed in syndromes caused by a mutated helicase (Bloom’s syndrome or Werner syndrome) or those caused by mutated protein upstream MRE11 function like ataxia telangiectasia or Nijmegen syndrome." (PMID 40429933, 2025). "The formation of MRE11 foci after irradiation appeared to be impaired in the ataxia telangiectasia cells tested with the same defined pattern of MRE11 foci." (PMID 35163494, 2022). "MRE11, RAD50, and NBS1 form the MRN complex in response to DNA damage to activate ATM, a gene responsible for Ataxia-Telangiectasia (A-T)." (PMID 35153719, 2021). "They include ataxia with oculomotor apraxia type 1 (AOA1) due to mutation in APTX2, ataxia with oculomotor apraxia type 2 (AOA2) caused by mutations in SETX3, ataxia telangiectasia (AT) due to mutation in ATM4, and the rarer AT like disorder (ATLD) linked to mutations in MRE11." (PMID 29127364, 2017).